IL6 (interleukin 6)
Diseases named in the same sentence as IL6 in open-access papers (continued):
Sharing a sentence is not in itself a finding about the gene and the disease.
Chlamydia infection (11 papers, 2012 to 2024). "Patients who received anti-IL-6 treatment were also found to be at increased risk of Chlamydia infection." (PMID 34093528, 2021). "Elevated IL-6 levels were found to play a protective role in controlling Chlamydia infection, given that IL-6 deficient mice were significantly more susceptible to Chlamydia infection through the airway than wild-type mice." (PMID 34093528, 2021). "Given this link between the ER stress response and RIP2 for il-6 mRNA associated with Chlamydia infection, it was of interest to examine whether this pathway affected bacterial clearance." (PMID 32487756, 2020). "From the perspective of the adaptive immune response, high expression of IL-6 activates the Th1-like response to clear pathogens by regulating the production of IFN-γ and thus decrease susceptibility to Chlamydia infection." (PMID 34093528, 2021). "Some of the most interesting discoveries are relevant to the varying role of IL-6 in Chlamydia infection at different inoculating doses." (PMID 34093528, 2021). "In summary, these data suggest that the in vivo production of IL-6 in response to Chlamydia infection requires the induction of an ER stress response." (PMID 32487756, 2020). "Again, IL-6 was consistently elevated 2 days after Chlamydia infection, but this response was reduced significantly in Chlamydia-infected mice treated with TUDCA." (PMID 32487756, 2020). "The induction of interleukin 6 (IL-6) production after systemic Chlamydia infection correlated with expression of ER stress response genes." (PMID 32487756, 2020). "Collectively, our data implicate a much more impactful role for NF-κB in the synthesis of IL-6 during Chlamydia infection of OE cells, and that NF-κB pathways play a lessor role in the early infection induction of IFN-β." (PMID 25798928, 2015). "Like other infectious organisms, Chlamydia infection of epithelial cells mucosal surface evokes proinflammatory cytokines such as interleukin (IL)-6, IL-8, and tumor necrosis factor (TNF)." (PMID 22529524, 2012). "Multiple studies have shown the need of IL-6 and IL-8 for an early optimal host response against Chlamydia infection." (PMID 22529524, 2012). "Studies have shown that after the activation of the innate immune system by Chlamydia infection, it can promote the release of numerous pro-inflammatory mediators such as IL-6, IL-8, and tumor necrotic factor-α, inhibiting Chlamydia replication and accelerating pathogen elimination." (PMID 36550834, 2022). "IL-6 can also be detected in the semen and serum of asymptomatic patients with Chlamydia infection." (PMID 34093528, 2021). "Chlamydia infection induces the unfolded protein response and IL-6 production." (PMID 32487756, 2020). "Given the correlation between the ER stress response and IL-6 production following Chlamydia infection, we examined whether these events might be connected." (PMID 32487756, 2020). "Using this convenient time point, we examined whether the ER stress inhibitor TUDCA affected the production of IL-6 in response to Chlamydia infection." (PMID 32487756, 2020). "Consistent in part with this, at 24 h post Chlamydia infection, human iPSdMs were shown, using Luminex bead-based multiplex assays, to express high levels of the pro-inflammatory cytokines IL-6 and TNFα, as well as IL-1β, chemokine IL-8 and the anti-inflammatory cytokine IL-10." (PMID 28440293, 2017). "While the immune mechanisms leading up to reproductive tissue damage in Chlamydia infections remain unclear, our findings highlight the involvement of mast cells in soluble mediator production, including IL-6, and suggest that TLR2 modulation may provide a mechanism to modify this cytokine response." (PMID 37138882, 2023). "Although IL-6 plays critical roles in controlling Chlamydia infections, the effects may vary." (PMID 34093528, 2021). "Thus, we examined whether IL-6 production in response to Chlamydia infection required the expression of RIP2." (PMID 32487756, 2020).
Chlamydia infection (continued). "Consistent with what we had observed in human cells, mouse cells KO for ISG15 displayed increased synthesis of IL6, and to a lesser extent of IL8 (KC), upon Chlamydia infection." (PMID 39345209, 2024). "Toll-like receptor 2 (TLR2) has been identified as an important receptor involved in the induction of IL-6, IL-8, granulocyte-macrophage colony-stimulating factor (GM-CSF), and TNF-α by epithelial cells or macrophages in response to Chlamydia infection." (PMID 32487756, 2020). "Like for H56, the cytokines IFN-γ, IL-6 and TNF-α were among the dominating cytokines in the CAF01, GLA-SE, and IC31® groups but only IFN-γ seemed to be selectively increased upon chlamydia infection." (PMID 26791076, 2016). "In a previously studied mouse model of Chlamydia infection, the complete lack of an IL-6 response resulted in less-severe tissue damage, but given the many roles of IL-6 in regulating immunity, the interpretation of the role of IL-6 at sites of acute infection remains undetermined." (PMID 37138882, 2023).
complication (11 papers, 2010 to 2025). Any disease or disorder that occurs during the course of, or because of, another disease, treatment, or procedure. "Alternatively, sample size studied was insufficient to analyze associations of IL-6 polymorphism with diabetic microvascular complications." (PMID 33016995, 2020). "In addition, the inclusion of this marker in a stepwise logistic regression with miR-21 and IL-6 revealed a significantly high association with the development of vascular complications in diabetic groups." (PMID 36139749, 2022). "The EURODIAB Prospective Complication Study hypothesized that a Z-score composed by C-reactive protein (CRP), Tumor Necrosis Factor-α (TNF-α), and interleukin-6 (IL-6) could be associated with the presence of vascular complications in diabetic patients." (PMID 27376090, 2016). "The observed induction of IL-6, IL-1β and TNFα in hypercoagulable diabetic mice is consistent with these observations and with the perception of diabetic vascular complications as inflammation-driven diseases." (PMID 35631132, 2022). "The observed induction of IL-6 and TNFα in glucose stressed macrophages is entirely congruent with these observations and with the perception of diabetic vascular complications as inflammation driven diseases." (PMID 30271984, 2018). "However, SSc patients with periodontal complications possess increased levels of matrix metalloproteinase-9 and chemokines, such as interleukin-6 and chemokine (C-X-C motif) ligand-4." (PMID 38779873, 2024). "Therefore, we suggest that IL-6 be considered a predictor for the development of vascular complications in the diabetic population." (PMID 36139749, 2022). "Likewise, IL-6 and TNF-α, in addition to a number of other cytokines, are excessively active in patients who have developed HCT-associated endothelial complications." (PMID 36733348, 2022). "Patients presenting with pulmonary complications exhibited significantly higher concentrations of IL-1β, IL-6, IL-12, and IFN-γ compared with those who presented without pulmonary complications." (PMID 24696530, 2014).
coronary stenosis (11 papers, 2013 to 2025). Narrowing of the coronary artery lumen diameter. "In this group, inflammatory cytokines TNFα and IL6 were the main factors directly related to the severity of coronary stenosis." (PMID 37762433, 2023). "IL-6 was found to be the most significant independent predictor of functional coronary artery stenosis detected through QFR." (PMID 34660716, 2021). "Our data confirm a correlation between increasing IL-6 plasma levels and severity of coronary stenosis, thus suggesting the proatherogenic role of this cytokine despite HIV-RNA suppression under HAART." (PMID 24383040, 2013). "Recently, our group demonstrated an association between serum IL-6 concentrations and subclinical CAD, in which high levels of serum IL-6 level (> 1 pg/mL) were predictive of coronary stenosis ≥ 30% in intermediate-risk patients referred for coronary angiography." (PMID 36028849, 2022). "IL-6 correlated independently with functional and anatomic coronary stenosis in our study." (PMID 34660716, 2021). "The study revealed that a combination of IL-6, IL-10, and CD4 + T lymphocytes outperformed individual biomarkers in predicting functional coronary artery stenosis." (PMID 38443781, 2024). "Furthermore, the combination of IL-6, IL-10, and CD4+ T lymphocytes is a better predictor of functional coronary stenosis than any single biomarker." (PMID 34660716, 2021). "Previously, we observed that higher levels of IL-6, but not CRP, were associated with increased prevalence of coronary stenosis ≥50% and greater coronary artery calcification score among HIV-infected men in the MACS." (PMID 30946765, 2019). "CAD patients showed higher IL-6, sIL-6Rα levels, and B/T ratio, but lower sgp130 levels than controls. sgp130 and B/T ratio could be valuable biomarkers for CAD diagnosis and assessing coronary stenosis severity in postmenopausal women." (PMID 39854741, 2025).
Ebola (11 papers, 2011 to 2025). "Some of the genes that had already been implicated in the pathogenesis of Ebola hemorrhagic fever such as IL-6 and TNF-α were induced after 1 h, but returned towards basal levels of expression after 6 h." (PMID 22028943, 2011). "Likewise, the severity of Ebola virus disease was statistically significantly associated with elevated plasma levels of several cytokines and chemokines such as IL-6, IL-8, IL-10, MCP-1 and MIP-1β during the acute phase of infection." (PMID 28106111, 2017). "ADAM-17 regulates IL-6 class switching as a mediator between pro- and anti-inflammatory responses to viral antigenic stimuli in Ebola, SARS-CoV and dengue infections in humans." (PMID 32256705, 2020). "These actions place IL-6 in a central role in mediating and amplifying cytokine release syndrome (CRS), commonly associated with Ebola virus disease (EVD) infections." (PMID 33071786, 2020). "It is postulated that IL-6 may play a role in the coagulopathy seen during Ebola virus disease (EVD) and MVD and in viral dissemination via recruitment of monocytes." (PMID 36016203, 2022). "Overall our data suggest that human clinical trials evaluating the benefits of α-IL-6 mAbs versus α-IL-6R mAbs titversus combined early α-IL-6 mAb and later α-IL-6R mAb is warranted to evaluate the potential of IL-6 pathway blockade in the during Ebola or SARS-CoV-2 infection." (PMID 33071786, 2020). "Taken together, Ebola seemingly triggers “immunological misfiring”111 in human ECs by elevating inflammatory cytokines (e.g., IL6 and CXCL8), in the virtual absence of interferon and antiviral ISGs." (PMID 41279810, 2025). "Indeed, IL6 and CXCL8 are elevated 100- to 1000-fold in Ebola patients, and can reach extremely high bloodborne levels (>1 ng/mL) in vivo." (PMID 41279810, 2025). "Similar cytokine patterns observed in our study in CCHF and HFRS patients, were seen also in patients with Ebola virus disease (EVD) where elevated levels of IL-1β, IL-1RA, IL-6, IL-8, IL-15, MIP-1α, MIP-1β, MCP-1, MCP-3, IP-10 and eotaxin were associated with fatal outcome." (PMID 31357521, 2019). "It’s important to note that fatal outcome from Ebola virus disease (EVD) correlates strongly with significantly higher IL-6 and IL-8 compared to non-fatal outcome, contrary to our results which show similar levels of both in fatal cases and survivors." (PMID 26437779, 2015).
encephalomyelitis (11 papers, 2012 to 2025). Inflammation of the brain and the spinal cord. "TRPV1 stimulation induces IL-6 amplification and exacerbates encephalomyelitis with excessive induction of other pro-inflammatory cytokines." (PMID 40823821, 2025). "In vitro, both vitamers were shown to limit the production of interleukin-6 (IL-6) and other proinflammatory cytokines through the inhibtion of nuclear factor kappaB whereas, in vivo, MK-4 limited inflammation in encephalomyelitis." (PMID 26959054, 2016). "Of note, recent findings highlighted the crucial role of dendritic cell-derived IL-6 in the development of experimental encephalomyelitis through the process called trans-presentation that may be a distinctive feature of this cellular source of IL-6." (PMID 30534125, 2018). "We also showed increase of tumour necrosis factor, IL-6 and CXCL10 in the transcriptomic analysis, which were also found in the cerebrospinal fluids of EV-A71 encephalomyelitis patients." (PMID 28724943, 2017). "Also, the knockout mice study of IL-6−/− and STAT3−/− develops encephalomyelitis resistant, which suggests the role of STAT3 in neuropathogenesis." (PMID 31484947, 2019).
endophthalmitis (11 papers, 2016 to 2025). An infectious process affecting the internal structures of the eye. "Indeed, our data show significant upregulation of JAK/STAT signaling and its associated genes/molecules, including IL-6, which implies an important role of this pathway in SA endophthalmitis." (PMID 26865111, 2016). "In the endophthalmitis group, there were seven positively correlated cytokine pairs, including IL-6/IL-23 and IL-33/IL12p70, which were positively correlated." (PMID 40563988, 2025). "To validate the role of identified immune mediators that were overexpressed in the pathogenesis of MDR-PA endophthalmitis, we analyzed the level of IL-6 and TNF-α by multiplex ELISA." (PMID 35046947, 2021). "The cytokine milieu in endophthalmitis was characterized by innate-related IL-6, tumor necrosis factor (TNF)-α, and IL-1β, which are involved in ocular barrier breakdown and leukocyte recruitment into ocular tissue." (PMID 34783307, 2021). "Moreover, cytokines such as interleukin (IL)-1, IL-6, IL-8, and tumor necrosis factor α, which can activate inflammatory cells in atherosclerotic plaque, have been found to be elevated during endophthalmitis." (PMID 36769859, 2023). "In the vitreous of patients with distinct clinical characteristics, an intensified inflammatory response involving IL-10, IL-6, IL-8, IL-1β, and TNF-α was observed in cases of MDR P. aeruginosa endophthalmitis compared to infections caused by sensitive P. aeruginosa." (PMID 37624004, 2023). "Our results demonstrated elevated expression of 16 mediators such as GCSF, GRO, IFN-γ, IL-1α, IL-1β, IL-1 RA, IL-6, IL-8, IP-10, MCP-1, MCP-3, MIP-1α, IL-1β, TGF-α, TNF-α in patients with culture positive endophthalmitis." (PMID 30296277, 2018). "We observed a wide variation in concentrations within the patients with endophthalmitis sample group for multiple cytokines, including MCP-3, GRO, IL-6, IL-8, IP-10, MCP-1α, IL-1α and IL-1ß." (PMID 30296277, 2018). "In an intradermal infection mice model, IL-1β, IL-6, TNF-α, and IFN-γ were produced by the lymph nodes only after MSSA infection; while in a murine model of endophthalmitis, IL-10, IL-15, IL-11, and some chemokines and receptors were significantly strongly upregulated by MRSA." (PMID 38571946, 2024).
falciparum malaria (11 papers, 2012 to 2025). "Tabone indicated in patients with acute Plasmodium falciparum malaria that IL-6 was inversely associated with vitamin A plasma concentrations." (PMID 36496428, 2022). "This study investigates the association between two APOA1 gene polymorphisms (G-75A and C+83T), APOA1 levels, and inflammatory markers (tumor necrosis factor-alpha and interleukin-6) in Nigerian children with uncomplicated Plasmodium falciparum malaria." (PMID 40061813, 2025). "To elucidate any possible consequences of the increased IL-27 levels in falciparum malaria, we examined the effect of IL-27 on the release of prototypical inflammatory cytokines (i.e., IL-6 and IL-8) in hemozoin-exposed HAoEC." (PMID 31964363, 2020). "We therefore, determined Cytokine profiles (IFN-γ, TNF-α, IL-6, TGF-β and IL-10) associated with Plasmodium falciparum malaria and soil borne helminth co-infections among patients attending Kampala International University Teaching Hospital in Uganda." (PMID 29560020, 2018). "Co-infected individuals expressed higher levels of IL-6 (100.9 pg/ml) as compared to Plasmodium falciparum malaria infected individuals (63.7 pg/ml) and soil borne helminths infected individuals (45.37 pg/ml)." (PMID 29560020, 2018). "Cytokine levels significantly differed across Plasmodium falciparum malaria, soil borne helminth infected patients and patients co-infected with Plasmodium falciparum malaria and soil borne helminth for IL-10 (P = 0.004), IL-6 (P = 0.011) and TGF-β (P = 0.003)." (PMID 29560020, 2018). "Contrary to the recent suggestion that P. vivax elicits more inflammation than P. falciparum, we found higher IL-10/TNF-α, IL-10/IFN-γ and IL-10/IL-6 ratios, but similar inflammatory cytokine responses per parasitized red blood cell, in vivax compared to falciparum malaria." (PMID 22973442, 2012). "Furthermore, TNF, IL-1, IL-6, etc., inflammatory genes are over-expressed in falciparum malaria." (PMID 36239109, 2022). "Lack of significant difference across groups in IL-6 could probably be because the IL-6 is not involved in modulation of the disease both in Plasmodium falciparum malaria infected individuals and soil borne helminths infected individuals." (PMID 29560020, 2018).
hypercortisolemia (11 papers, 2009 to 2026). "Our findings are in agreement with previous studies reporting that circulating levels of IL6 are high in patients with overt hypercortisolism." (PMID 31649930, 2019). "Proinflammatory cytokines (IL-1, IL-6, TNF-α) in chronic disease may cause HPA axis hyperactivity by disturbing the negative feedback inhibition of circulating cortisol, which creates a condition of hypercortisolemia." (PMID 37916198, 2023). "Statistically, femoraladipose tissue IL-6 release was not different from zero (femoral IL-6 release,control, 1.14 ± 0.56 pg/mL/100 g tissue; hypercortisolemia, −0.28± 2.86 pg/mL/100 g tissue; P = 0.077 and P =0.925, respectively; one-sample t test compared with zero)." (PMID 28323916, 2017).